TBX10 (T-box transcription factor 10)
Description:
Probable transcriptional regulator involved in developmental processes.
Synonyms: TBX7; TBX13
Tractability: No criterion of Open Targets' tractability assessment is met for any kind of drug.
Gene: Protein-coding gene on chromosome 11 (67,631,303 to 67,639,763, reverse strand). Ensembl gene ENSG00000167800.
Subcellular location: Nucleus
Subcellular location (Human Protein Atlas): Nucleoplasm; Cytosol
Gene Ontology:
Molecular function: DNA-binding transcription factor activity, RNA polymerase II-specific; RNA polymerase II cis-regulatory region sequence-specific DNA binding; DNA-binding transcription factor activity
Biological process: anatomical structure morphogenesis; cell fate specification; regulation of transcription by RNA polymerase II; positive regulation of DNA-templated transcription; regulation of DNA-templated transcription
Cellular component: chromatin; nucleus
Genetic constraint (gnomAD): Loss-of-function variants: 26 observed, 33.73 expected, observed/expected ratio (o/e) 0.77, 90% interval 0.56 to 1.07. The upper end of that interval is the gene's LOEUF score, 1.07, which puts it in group 4 of 6, group 1 being the genes least tolerant of losing a copy. Missense variants: 490 observed, 492.47 expected, observed/expected ratio (o/e) 0.99, 90% interval 0.92 to 1.07. Synonymous variants: 195 observed, 199.6 expected, observed/expected ratio (o/e) 0.98, 90% interval 0.87 to 1.1.
Homologues: Orthologues: chimpanzee TBX10 (99% identical), macaque TBX10 (96% identical), pig TBX10 (85% identical), guinea pig TBX10 (83% identical), dog TBX10 (83% identical), Drosophila melanogaster mid (32% identical), Drosophila melanogaster H15 (31% identical), Caenorhabditis elegans mab-9 (29% identical), Drosophila melanogaster ocm (28% identical), Caenorhabditis elegans tbx-8 (24% identical), Caenorhabditis elegans tbx-9 (22% identical), Caenorhabditis elegans tbx-37 (21% identical), and 4 more. Paralogues in human: TBX1 (59% identical), TBX2 (37% identical), TBX3 (36% identical), TBX18 (36% identical), TBX15 (35% identical), TBX4 (35% identical), TBX5 (35% identical), TBX20 (34% identical), MGA (34% identical), TBX6 (33% identical), TBX22 (32% identical), TBR1 (31% identical), and 4 more.
Diseases named in the same sentence as TBX10 in open-access papers:
TBX10 is named in the same sentence as 6 diseases in open-access papers, as found by Europe PMC text mining. Sharing a sentence is not in itself a finding about the gene and the disease. The quoted sentences say what the papers report.
colorectal cancer (1 paper, 2024). A primary or metastatic malignant neoplasm that affects the colon or rectum. "Among the regulons driving classical states were those driven by TBX10, PDX1, FOXA3 and CDX2, which is a known prognostic marker in gastrointestinal cancers, especially colorectal cancer, and has been described as a lineage survival oncogene." (PMID 39417106, 2024).
congenital heart disease (1 paper, 2017). A heart disease that is present at birth. "Variations in NOTCH2, NOTCH3, TTN, TBX4, TBX10, TBX18, and TBXAS1 are associated with congenital heart disease." (PMID 29381953, 2017).
cyst (1 paper, 2024). A sac-like closed membranous structure that may be empty or contain fluid or amorphous material. "In the present study, we discovered that key TFs such as LMX1B and TBX10, which play critical roles in cell differentiation and organ development, are significantly down-regulated in the cyst stage of T. rubra." (PMID 39009560, 2024).
cancer (1 paper, 2020). A tumor composed of atypical neoplastic, often pleomorphic cells that invade other tissues. "Using the 5 patients with both normal and cancer cells profiled, we estimated the frequency of inactivation of all 56 colon-specific TFs across the 5 patients, which revealed that CDX2 and TRIM31 were inactivated in 80% of the patients, whereas ATOH1, HNF4A, CDX1, and TBX10 were inactivated in 60%." (PMID 33083012, 2020).
TBX10 also shares sentences with these, for which no sentence is quoted: Hodgkins lymphoma (1 paper); orofacial cleft (1).